PRKCSH (PRKCSH beta subunit of glucosidase II)
Diseases named in the same sentence as PRKCSH in open-access papers (continued):
Sharing a sentence is not in itself a finding about the gene and the disease.
hepatoma (2 papers, 2019 to 2024). "TM treatment also increased the association between endogenous PRKCSH and IRE1α in Huh-7 hepatoma cells." (PMID 31320625, 2019). "Immunoblot analysis also showed that the expression level of PRKCSH is increased in hepatoma cell lines (HepG2 and Huh-7) compared to that of normal liver cell lines (CCL-13 and L02)." (PMID 31320625, 2019). "In hepatoma cells, where the expression level of PRKCSH is high, interaction of both proteins is relatively lasting and results in sustained phosphorylation of IRE1α and MAPKs." (PMID 31320625, 2019). "In Huh-7 hepatoma cells, the oligomerization of IRE1α was drastically increased upon TM treatment (up to 65% foci-positive cells), whereas silencing PRKCSH in this cell line considerably reduced it under ER stress (up to 30% foci-positive cells)." (PMID 31320625, 2019). "PRKCSH-silenced hepatoma cells and Huh-PRK KO cells showed a remarkable reduction in IRE1α phosphorylation upon TM treatment." (PMID 31320625, 2019). "Analysis of co-localization of PRKCSH and calnexin showed that PRKCSH is primarily localized in the ER in hepatoma cells, indicating that the PRKCSH level is increased in the ER of these cells in comparison with normal liver cells." (PMID 31320625, 2019). "Conversely, PRKCSH silencing in HepG2 and Huh-7 hepatoma cells significantly attenuated TM-induced expression of these genes." (PMID 31320625, 2019). "To investigate the potential role of PRKCSH in the regulation of the ER stress response in HCC cell models, we compared the levels of spliced XBP1 and activated MAPKs between PRKCSH-silenced and control hepatoma cells." (PMID 31320625, 2019). "Silencing PRKCSH in both hepatoma cell lines decreased the level of spliced XBP1 protein." (PMID 31320625, 2019). "Furthermore, the expression levels of IRE1α–XBP1 target genes were also decreased by PRKCSH silencing in Huh-7 hepatoma cells." (PMID 31320625, 2019). "Furthermore, we previously reported that PRKCSH may regulate the tumorigenesis of hepatocellular carcinoma by enhancing the activity of IRE1, a representative sensor of the ER stress response." (PMID 38200153, 2024). "The effect of PRKCSH on TNFSF resistance can be observed in various cancer cells, including lung, colon, and hepatoma cells." (PMID 38200153, 2024). "However, we did not observe nuclear localization of PRKCSH in liver tumor tissues or hepatoma cells." (PMID 31320625, 2019).
acute myeloid leukemia (1 paper, 2024). Acute myeloid leukemia (AML) is a group of neoplasms arising from precursor cells committed to the myeloid cell-line differentiation. "PRKCSH’s role extends beyond solid tumors; it has been reported to regulate hematopoietic stem cell (HSC) function, with high expression predicting poor survival in acute myeloid leukemia (AML) patients." (PMID 38571496, 2024).
astrocytoma (1 paper, 2024). "We found that missense mutations are the main type of mutation in PRKCSH, with L5P alteration detected in one case of astrocytoma, one case of uterine Endometrioid, and one case of colon adenocarcinoma." (PMID 38245572, 2024).
autosomal dominant polycystic kidney disease (1 paper, 2015). Autosomal dominant form of polycystic kidney disease. "In the case of a germline PRKCSH mutation in ADPLD, the second hit could involve a somatic PRKCSH or SEC63 mutation on the other allele, or somatic hits on genes implicated in Autosomal Dominant Polycystic Kidney Disease (ADPKD), such as PKD1 and PKD216." (PMID 26671672, 2015).
ciliopathy (1 paper, 2023). A genetic disorder of the cellular cilia or the cilia anchoring structures, the basal bodies, or of ciliary function. "Variants in PKD1 and PKD2 comprised 85.3% of the positive findings in this group, and other ciliopathy-associated genes (ALG9, PRKCSH, OFD1) accounted for an additional 3%." (PMID 37794564, 2023).
colorectal cancer (1 paper, 2025). A primary or metastatic malignant neoplasm that affects the colon or rectum. "This study investigated the role of PRKCSH in colorectal cancer radioresistance and its underlying mechanisms." (PMID 40189587, 2025). "Our results demonstrate that PRKCSH is upregulated in colorectal cancer cells following ionizing radiation." (PMID 40189587, 2025).
gastric cancer (1 paper, 2024). A primary or metastatic malignant neoplasm involving the stomach. "The role of PRKCSH in oncogenesis was initially suggested by an investigation of somatic mutations in the GAG stretch of the PRKCSH gene in gastric cancer, and a significant association was found between PRKCSH GAG mutations and a high level of microsatellite instability (MSI-H)." (PMID 38571496, 2024).
rectal cancer (1 paper, 2025). A primary or metastatic malignant neoplasm that affects the rectum. "In rectal cancer patients receiving neoadjuvant radiotherapy, higher PRKCSH expression in post-treatment samples correlated with reduced tumor regression." (PMID 40189587, 2025). "Furthermore, PRKCSH expression may serve as a biomarker for evaluating radiotherapy efficacy and clinical outcomes in rectal cancer patients undergoing neoadjuvant therapy." (PMID 40189587, 2025).
sarcoma (1 paper, 2024). A usually aggressive malignant neoplasm of the soft tissue or bone. "High PRKCSH expression was associated with poor prognosis in bladder, kidney, brain, lung, and sarcoma patients." (PMID 38245572, 2024).
staphylococcus aureus infection (1 paper, 2024). An infectious process in which the bacteria Staphylococcus aureus is present. "KEGG pathway analysis unveiled that PRKCSH was mainly involved in viral protein interaction with cytokine and cytokine receptors, staphylococcus aureus infection, hematopoietic cell lineage, and cytokine-cytokine receptor interaction." (PMID 38245572, 2024).
tumor (9 papers, 2019 to 2025). "Reduced PRKCSH expression has been associated with impaired protein folding, increased ER stress and anti-tumor immunity." (PMID 41007761, 2025). "We showed using zebrafish xenografts that PRKCSH knockout (KO) causes a reprogramming of the tumor immune microenvironment, which is characterized by an elevated M1/M2 macrophage ratio, and hinders tumor proliferation in vivo." (PMID 41350724, 2025). "Along with immune modulation, loss of PRKCSH made tumor cells more vulnerable to ER stress-induced cell death, such as apoptosis and ferroptosis, while also compromising autophagy." (PMID 41350724, 2025). "Conversely, they found a positive association between PRKCSH expression and the infiltration of M2 macrophages in twelve tumor types." (PMID 38571496, 2024). "Then we explored the potential mechanisms underlying the high expression of PRKCSH mRNA in tumor cells." (PMID 38245572, 2024). "We assessed aberrant PRKCSH mRNA and protein expression, examined its prognostic implications, and identified correlations with clinical features, tumor mutational burden (TMB), microsatellite instability (MSI), and tumor immunity across cancer types." (PMID 38245572, 2024). "Tumor sphere size was significantly reduced by TRAIL treatment in PRKCSH-deficient cells, whereas it was restored by treatment with caspase-8 and pan-caspase inhibitors." (PMID 38200153, 2024). "To investigate the relevance of caspase-9 activity in TNFSF sensitization in PRKCSH-deficient cells, we investigated the effect of a caspase-9 inhibitor on tumor sphere formation." (PMID 38200153, 2024). "Loss of PRKCSH reduced in vivo tumor growth under physiological stress condition." (PMID 31320625, 2019). "Targeting PRKCSH may have several therapeutic advantages, including reestablishing immune surveillance through M1 reactivation, making tumors more susceptible to apoptosis and ferroptosis, and disrupting stress-adaptive systems that promote tumor survival." (PMID 41350724, 2025). "In contrast, PRKCSH-knockout tumor cells (PRKCSH [−]) show hyperactivation of the IRE1α axis, increased XBP1s and p-JNK levels, and enhanced cell death via apoptosis and ferroptosis, alongside reduced autophagy." (PMID 41350724, 2025). "We examined the levels of INF-γ, Granzyme B, and PD-1 in human PBMCs that had been injected with either WT-A549 or PRKCSH-KO A549 cells to investigate how T cells killed tumor cells and how the immune system was activated." (PMID 41350724, 2025). "In conclusion, our findings place PRKCSH as a key regulator linking ER stress signaling with tumor immune evasion and cell death pathways." (PMID 41350724, 2025). "By controlling IRE1α activity and IL-6/IL-8 secretion, these results imply that PRKCSH influences macrophage behavior and the inflammatory landscape of the tumor microenvironment in an indirect but significant way." (PMID 41350724, 2025). "There are still a few restrictions even though this study shows PRKCSH to be a crucial modulator of tumor immunity and stress reactions." (PMID 41350724, 2025). "By contrast, PRKCSH was significantly positively correlated with TGFB1, a cytokine linked to M2-like, immunosuppressive programming in the tumor microenvironment." (PMID 41350724, 2025). "Under ER stress, PRKCSH-expressing tumor cells (PRKCSH [+]) exhibit moderate activation of the IRE1α–XBP1–JNK pathway and secrete IL-6 and IL-8, promoting tumor survival and supporting M2 macrophage polarization." (PMID 41350724, 2025). "Using the scCancerExplorer platform, we examined three single-cell RNA sequencing datasets (GSE127465, GSE117570, and GSE162498) to investigate the relationship between PRKCSH expression and macrophage phenotypes within the tumor microenvironment." (PMID 41350724, 2025). "Based on these findings, we aim to further investigate how elevated PRKCSH expression influences macrophage polarization and function, particularly in the context of immune suppression and tumor progression." (PMID 41350724, 2025).
tumor (continued). "The resulting decrease in the M1/M2 ratio in MPE underscores a shift toward an immunosuppressive tumor microenvironment and supports the translational relevance of PRKCSH-mediated immune modulation." (PMID 41350724, 2025). "We did macrophage stimulation tests with conditioned media from A549 tumor cells (WT and PRKCSH-KO) to investiagte how the macrophage phenotype changed." (PMID 41350724, 2025). "This means that losing PRKCSH in vivo creates a tumor microenvironment that promotes immune response." (PMID 41350724, 2025). "PRKCSH facilitates tumor cell survival and immune evasion by modulating cytokine secretion, macrophage polarization, and ER stress responses." (PMID 41350724, 2025). "This study aimed at exploring the prognosis predictive potential and tumor immunity function of PRKCSH in malignancies, offering insights into novel immunotherapy strategies." (PMID 38245572, 2024). "Compared to the control group, the PRKCSH-depleted group of A549 cells showed dose-dependent reductions in tumor sphere formation in response to both TRAIL and TNF-α." (PMID 38200153, 2024). "Consistent with the tumor sphere formation results, PRKCSH depletion also accelerated TRAIL- and TNF-α-mediated cell death in A549 cells." (PMID 38200153, 2024). "PRKCSH deficiency augmented the antitumor effects of natural killer (NK) cells, representative TNFSF effector cells, in a tumor xenograft IL-2Rg-deficient NOD/SCID (NIG) mouse model." (PMID 38200153, 2024). "Taken together, these results cast illumination on the critical function of PRKCSH in regulating tumor immunity by interacting with TME, though further proof of experiments is required." (PMID 38245572, 2024). "Taken together, these results show that PRKCSH contributes to the adaptation of tumor cells against TNFSF cytotoxicity by increasing the half-life of IGF1R, which is involved in tumor resistance to antitumor immunity and various cancer therapeutics." (PMID 38200153, 2024). "Genetic variations in PRKCSH were identified across 26 tumor types, suggesting favorable disease-free survival." (PMID 38245572, 2024). "Then, we sought the links between PRKCSH expression and a variety of immune signatures to enlarge the comprehension of the function of PRKCSH in tumor immunity." (PMID 38245572, 2024). "PRKCSH mRNA expression was significantly elevated in 19 types of tumors compared to their normal tissues among 23 tumor types in TCGA." (PMID 38245572, 2024). "Caspase-9 inhibition restored the TRAIL-mediated reduction in tumor sphere size and strongly suppressed TRAIL-mediated cell death and caspase-9 activation in PRKCSH-deficient cells." (PMID 38200153, 2024). "Elevated levels of PRKCSH expression are positively correlated to tumor stage and lymph node metastasis." (PMID 38245572, 2024). "The IRE1α signaling pathway, a crucial component of the unfolded protein response (UPR) reported to be directly activated by PRKCSH, plays a multifaceted role in the context of anti-tumor immunity." (PMID 38571496, 2024). "Histological data revealed that PRKCSH depletion enhanced the sensitivity of NK cell-mediated tumor cell death and NK cell infiltration into the tumor tissues." (PMID 38200153, 2024). "PRKCSH was generally more expressed in higher tumor stages (stage III or IV vs. I or II), especially in ACC (stage III vs. I, stage IV vs. I, stage III vs. II, stage IV vs. II) and KICH (stage II vs. I, stage IV vs. I, stage IV vs. II, stage IV vs. III)." (PMID 38245572, 2024). "PRKCSH is also involved in tumor immunity and correlated with various immune cells and immune molecules." (PMID 38245572, 2024). "We also predicted small molecule drugs targeting PRKCSH using the Cmap database, some of which have already been used in tumor treatment or prevention." (PMID 38245572, 2024). "The tumor spheroid assay showed that PRKCSH depletion (shPRK) in A549 cells increased the sensitivity to NK-92 cell-mediated cytotoxicity compared to that in the control group (shCon)." (PMID 38200153, 2024).
tumor (continued). "Consistently, PRKCSH expression was detected to be elevated in RCC, and PRKCSH overexpression contributed to a reversal of the anti-tumor effect of circCOL5A1 silencing." (PMID 37660068, 2023). "IHC staining observed lower HK2 and PKM2 expression in tumors after circCOL5A1 knockdown, and Western blot assessed lower protein expression of tumor PRKCSH and Ki-67." (PMID 37660068, 2023). "All in all, this research summarizes the tumor-promoting effect of circCOL5A1 in the field of glycolysis by competing with miR-370-5p to release PRKCSH expression." (PMID 37660068, 2023). "PRKCSH is involved in induction of tumor-promoting factors and tumor resistance to ER stress by selective activation of IRE1 branch of UPR." (PMID 36500393, 2022). "Our data provide strong evidence that PRKCSH can be a useful tumor marker in various cancer tissues and protects tumor cells from ER stress by promoting IRE1α activity." (PMID 31320625, 2019). "Increased levels of PRKCSH in various tumor tissues are positively correlated with the expression of XBP1-target genes." (PMID 31320625, 2019). "Next, we investigated the effect of PRKCSH on the regulation of ER stress-induced expression of tumor-promoting factors." (PMID 31320625, 2019). "To investigate the association of PRKCSH with tumorigenesis, we analyzed the relative expression levels of PRKCSH by using the complete data sets of human tumor tissues of The Cancer Genome Atlas (TCGA)." (PMID 31320625, 2019). "Overall, these results suggest that the PRKCSH–IRE1α signaling axis is crucial for adaptation of tumor cells to ER stress." (PMID 31320625, 2019). "PRKCSH contributes to the induction of tumor-promoting factors and to tumor resistance to ER stress." (PMID 31320625, 2019). "Subsequently, we also analyzed PRKCSH expression in human tumor tissues using the data available from the National Center for Biotechnology Information (NCBI) Gene Expression Omnibus (GEO) database." (PMID 31320625, 2019). "In preclinical CRC models, PRKCSH depletion suppressed tumor growth and increased radiosensitivity." (PMID 40189587, 2025). "Together, our results establish PRKCSH as a complex modulator of immune escape and tumor cell survival that combines cytokine-mediated immune modulation and ER stress adaptation to promote a tumor-permissive environment." (PMID 41350724, 2025). "Our study demonstrated that PRKCSH plays a crucial role in maintaining cytokine-driven immunosuppressive signaling, which may otherwise promote tumor progression in part through M2 reprogramming." (PMID 41350724, 2025). "Despite this overall reduction, macrophages remained the most abundant immune cell type, suggesting that macrophages may play a dominant role in shaping the tumor immune landscape in PRKCSH-high LUAD cases." (PMID 41350724, 2025). "Subsequently, we examined the relationship between the PRKCSH expression and tumor stage." (PMID 38245572, 2024). "Notably, PRKCSH expression demonstrated variations across disease stages, primarily increasing in advanced stages among eleven tumor types." (PMID 38245572, 2024). "Thus, we analyzed the correlation between the PRKCSH level and the infiltration levels of 22 non-tumor cells in the TME." (PMID 38245572, 2024). "Overall, these results suggest the potential role for PRKCSH in tumor immunity regulation." (PMID 38245572, 2024). "Furthermore, our analysis of CCLE data demonstrated distinct PRKCSH mRNA expression levels in 32 tumor cell lines, with the THCA cell line exhibiting the highest levels and the DLBC cell line displaying the lowest levels." (PMID 38245572, 2024). "However, the key role of PRKCSH in tumor resistance against TNFSF- and NK cell-mediated cytotoxicity has not yet been investigated." (PMID 38200153, 2024). "Thus, our data suggest that PRKCSH contributes to tumor resistance against various cancer therapeutics as well as the TNFSF response via Mcl-1 mRNA transcription regulation." (PMID 38200153, 2024).